CD9 (CD9 molecule)
Diseases named in the same sentence as CD9 in open-access papers (continued):
Sharing a sentence is not in itself a finding about the gene and the disease.
melanoma (continued). "The dNK cell decidual marker CD9 is expressed by TI-NKs of melanoma, colorectal cancer, breast cancer, and glioblastoma." (PMID 35712510, 2022). "In these analyses we observed the presence of big vacuolar structures in these melanoma cells, which were greatly reduced in number in CD9 KO and, to a lower extent, upon CD9 peptide treatment." (PMID 34012515, 2021). "One of the protein groups that are significantly altered in EVs from CD9 KO cells are mitochondrial components, further suggesting that EVs are part of the route for mitochondrial degradation at least in melanoma cells." (PMID 34012515, 2021). "Overexpression of CD81 partially rescued the infertility phenotype seen in CD9 KO mice and it was recently demonstrated that CD9 deletion in human melanoma cells was quickly compensated by CD63 expression upregulation." (PMID 34847198, 2021). "Our data thus provide the first evidence for a functional connection of tetraspanin CD9 with mitophagy in melanoma cells." (PMID 34012515, 2021). "Co-expression of CD9/CD81 was shown to regulate TGF-β1 signaling in melanoma by providing critical support for the TGFβR2-TGFβR1 association, which in turns favors epithelial to mesenchymal transition-like changes, invasion, and metastases." (PMID 33669943, 2021). "Both CD63 and CD9 play a role in melanoma progression and metastasis, although most classical reports were based on tetraspanin overexpression." (PMID 34012515, 2021). "Besides its physiological functions, CD9 is widely associated with diseases: both the up-regulation and down-regulation of CD9 are linked with poor prognosis in several types of cancer, such as melanoma, leukemia, and gastric, lung, breast, colon, and prostate malignancies." (PMID 32958604, 2020). "To monitor the intracellular transport of proteins, we used fluorescent EVs containing CD9‐green fluorescent protein fusion protein and various melanoma cell lines and bone marrow‐derived mesenchymal stromal cells as recipient cells." (PMID 30982221, 2019). "To determine the functionality of CD9 Fab, we evaluated its binding to melanoma FEMX‐I cells by various methods." (PMID 30982221, 2019). "Reduced CD9 expression has been correlated with poor prognosis in several types of cancers, including melanoma, lung, breast, colon, prostate, pancreatic ovarian, and prostate, reviewed in Ref." (PMID 29946318, 2018). "Comparing EVs from plasma of melanoma patients and healthy controls, we found that the signals of 5 out of 39 investigated proteins differed significantly and by at least 30%, namely CD9, CD8, CD29, CD42a, and CD62P." (PMID 27507971, 2016). "CD9 expression is correlated with poor prognosis of gastric cancer whereas the expression in melanomas, myelomas, and head and neck squamous carcinomas is associated with early stages of cancer progression and positive treatment outcome." (PMID 26036626, 2015). "The authors found that, although CD9 expression is reduced in the transition from melanocytes to melanoma, the re-expression of CD9 in specific melanoma cells alters the microenvironment of the tumor and leads to the enhanced invasion to Matrigel." (PMID 24520284, 2014). "While an inverse correlation between CD9 expression and metastatic development was observed in melanoma, cervical carcinoma and multiple myeloma, up-regulation of CD9 was demonstrated in aggressive gastric carcinoma and high-grade astrocytic tumors." (PMID 24466195, 2014). "In melanoma, CD9 re-expression was also observed in tumor vessels, suggesting that this protein is involved in tumor angiogenesis and in EC migration." (PMID 24520284, 2014). "In human melanoma, the CD9 tetraspanin protein appears to contribute to the transendothelial invasion of cancer cells by stimulating MMP-2, which degrades the extracellular matrix (ECM) surrounding ECs." (PMID 24520284, 2014). "Levels of CD9 were increased on CD45+ leukocytes isolated from LNs resected from melanoma patients with reduced DMFS." (PMID 24435119, 2014).
melanoma (continued). "Among these, endothelial CD9 was shown to actively redistribute to points of melanoma insertion, and anti-CD9 antibodies were found to inhibit migration of melanoma cells through HUVEC monolayers." (PMID 23344048, 2013). "A subset of NK cells in melanoma patients also expresses CD9, which is characteristically expressed only on NK cells within the female reproductive tract." (PMID 21403861, 2011). "In the research on malignant melanoma, it was found that CD9+ exosomes derived from CAFs have a significant inhibitory effect on the proliferation of malignant melanoma cells, and compared with CD9- patients, CD9+ patients have better disease-free survival rates." (PMID 40626005, 2025). "Bead-based multiplex analysis revealed the robust expression of the sEV tetraspanins CD9, CD63, and CD81 in addition to CD29 (Integrin beta- 1), the MSC-EV-specific markers CD44 (hyaluronic acid receptor) and MSCP/NG2 (melanoma‐ associated chondroitin sulfate proteoglycan)." (PMID 38764077, 2024). "Importantly, active redistribution of endothelial CD9 was also observed during interactions between melanoma and endothelial cells in an intravasation assay." (PMID 37007105, 2023). "Interestingly, CD9 was re-expressed in 46% of intermediate and thick melanomas in small tumor clusters predominantly located at sites of invasion near or inside the blood or lymphatic vessels." (PMID 35563166, 2022). "Moreover, it has been showed that melanoma cells’ transendothelial migration was inhibited by anti-CD9 monoclonal antibodies." (PMID 35563166, 2022). "Finally, we confirm that CD9 expression is consistent with an early protective role against tumorigenesis, however, our data endorse in melanoma a specific function of CD9 in vascular dissemination during late tumor progression." (PMID 35563166, 2022). "Also, differences in CD9 expression on EVs were observed in melanoma patients undergoing immunotherapy." (PMID 36203609, 2022). "Therefore, in vitro studies on transendothelial migration of melanoma cells highlight the significant role of CD9 in tumor–endothelial/lymphatic cell interaction and vascular dissemination of tumor cells." (PMID 35563166, 2022). "The most notable finding is that all CD9 stained melanomas presented sentinel node positivity." (PMID 35563166, 2022). "The fact that CD9 expression was found only in melanomas with lymph node metastases highlights that CD9 could be a promising biomarker for predicting SLN positivity, although support by further studies is needed." (PMID 36613587, 2022). "Interestingly, CD9 expression was restored in 30% and in 70% of the intermediate and thick melanomas, respectively, even if confined to several small clusters of tumor melanocytic cells." (PMID 35563166, 2022). "The presence of CD9 hotspots could be essential for melanoma cell invasion in lymphatic and endothelial vessels." (PMID 35563166, 2022). "However, it has been demonstrated that B16 mouse melanoma cells overexpressing CD9 showed increased capacity to invade Matrigel, although CD9 positivity in mouse and human melanoma cell lines was found to be reduced with respect to normal melanocytes." (PMID 35563166, 2022). "Similarly, we observed that CD9 expression was present in all nevi but lost in the totality of thin melanomas and in 52 of intermediate and thick melanomas (63%)." (PMID 35563166, 2022). "Therefore, we decided to make repeated treatments to melanoma cells during a 7d period with peptides of CD9, a scrambled control or CD63 as a specificity control." (PMID 34012515, 2021). "Here we have studied the effects of CD9 cytopermeable peptides on EV secretion in a melanoma model." (PMID 34012515, 2021). "By impeding intercellular communication in the tumour microenvironment, CD9 Fab‐mediated inhibition of EV uptake, combined with direct targeting of cancerous cells could lead to the development of novel anti‐melanoma therapeutic strategies." (PMID 30982221, 2019).
melanoma (continued). "MICA expression on melanoma-derived exosomes could be detected by LFIA using anti-CD9 for capture and anti-MICA for detection." (PMID 29720199, 2018). "Interestingly, while melanoma cells had reduced CD9 expression relative to normal melanocytes, forced increase in CD9 expression stimulated their invasiveness." (PMID 25762645, 2015). "Besides promoting metastasis through interaction with ECs, melanoma cells with high levels of CD9 become more motile." (PMID 24520284, 2014). "Also, we identified that melanoma-derived LEVs may be more enriched with CD9, CD63 and CD81 than nevi-derived EVs." (PMID 41268555, 2025). "We found that miR-195-5p overexpression in BRAF-mutated melanoma cells causes an increase in the expression levels of some EVs biogenesis-related genes like RAB27b, RAB31, and/or FLOT2, which was accompanied by a consequent increase in CD63 and CD9 positive EVs secretion." (PMID 37174717, 2023). "Furthermore, knocking-out CD9 in SK-MEL-147 melanoma cells also resulted in an increased number of lysosomes, supporting the notion that the association of ALCAM and CD9 may constitute a functional unit in cancer cells." (PMID 35628559, 2022). "Statistical analysis revealed that CD9 staining was directly related to the thickness of the primary melanomas (p < 0.0001); it was absent in all thin melanomas, while 16 cases of 56 intermediate melanomas (29%) and 28 of 40 thick melanomas (70%) showed CD9 positive clusters (p < 0.05)." (PMID 35563166, 2022). "In addition, MICA+ EVs from this melanoma cell line contained more CD81 than CD9." (PMID 36726591, 2022). "However, it was established that the cell surface protein EWI-2 negatively regulated TGF-β signaling in melanoma by sequestering CD9 (and CD81) and thereby impeding complex formation between TGFβ receptor 1 (TβR1) and TGFβ receptor 2 (TβR2), leading to diminished TGF-β signaling." (PMID 33424923, 2020). "Thus, we recommend optimizing coating of detection antibody to AuNP in a non-saturating concentration range, since the signal can be later enhanced by immobilising in the test line a capture antibody directed against abundant tetraspanins, like CD9 in our melanoma cell model." (PMID 29720199, 2018). "However, the average signal differences between healthy citrate plasma EVs and melanoma heparin plasma EVs for each of the five markers (CD9, CD8, CD29, CD42a, and CD62P) were at least equal or even more pronounced as compared to the differences of the heparin plasma samples." (PMID 27507971, 2016). "Of note, to better explore LEVs markers, we demonstrate tetraspanin labelling (CD9, CD63 and CD81) in our LEVs isolates from pooled plasma samples from nevi and melanoma patients." (PMID 41268555, 2025). "Of the three tetraspanins (CD9, CD63, and CD81) we have studied in the context of melanoma, only CD81 affects patient survival." (PMID 40521809, 2025). "The identification of all the exosomes derived from all three melanoma cell lines was further confirmed by the exosomal markers CD63, CD9, and CD81 using immunoblotting." (PMID 39123364, 2024). "PEVs also influenced the melanoma spheroids’ own EV production by modifying their tetraspanin (CD63, CD9, and CD81) profiles." (PMID 39695652, 2024). "Recent data showed that CAF-released EVs enriched CD9 and CD63, and inhibited the proliferation of melanoma cells remarkably." (PMID 37575250, 2023). "Essentially, in human MSCs, ionomycin increased cellular CD9 expression, which reduced CCL21 secretion by MSCs, which lessened chemoattraction and thereby decreased the migration of melanoma cell line." (PMID 35103937, 2022). "TA-NKs express CD9 and CD49+ in NSCLC, prostate cancer, and melanoma, and CXCR4 is present in TA-NKs of prostate cancer." (PMID 35712510, 2022). "In contrast, dextran-coated IONPs reduced MSC’s cellular expression of CD9, showed unaltered CCL21 secretion by MSCs (compared to control) and therefore unaltered chemoattraction and migration of melanoma cell line." (PMID 35103937, 2022).
melanoma (continued). "However, in most advanced-stage melanomas, as we have observed, CD9 re-expression within the tumor microenvironment may lead to enhanced invasion, suggesting that the decreased of CD9 expression occurs in the earliest stage of melanoma while it is re-expressed in the invasive stage." (PMID 35563166, 2022). "Both CD9 and CD63 are important regulators of melanoma progression and metastasis, so we decided to use a human melanoma cell line for our studies." (PMID 34012515, 2021). "Both CD9 and CD63 are important regulators of melanoma progression and metastasis, and EVs have been reported to play a fundamental role in tumour metastatic niche formation." (PMID 34012515, 2021). "All these data support a role for CD9 in lysosomal increment during starvation and in the formation of big LC3 positive degradative vacuoles in melanoma cells." (PMID 34012515, 2021). "Mel1 exosomes were positive for CD9, CD63 and Alix exosomal markers, and also for CD271 melanoma CSC marker." (PMID 33052601, 2021). "In early stage melanoma cells, when TGFβ signaling is low, EWI-2 is strongly expressed and interacts with CD9 and CD81, thereby sequestering CD9 and CD81 from the TGFβ receptor complex." (PMID 32274581, 2020). "Yet, all tested anti-CD9 mAbs (VJI/10, VJI/20, and GR2110) inhibited the trans-endothelial migration of melanoma cells." (PMID 29946318, 2018). "In these particular melanoma vesicles, the expression levels of tetraspanins CD81 and CD9 as well as of MHC-I are limited, so that their changes in MFI values are small throughout the range of sample dilutions." (PMID 28900146, 2017). "Recently a study on the tetraspanin-interacting protein EWI-2 indirectly implicates two other tetraspanins, CD9 and CD81, in regulating TGFβ signaling in melanoma growth and metastasis." (PMID 25978409, 2015). "The patients with CAF-derived CD9-positive EVs displayed a better five-year disease-free survival than patients with CD9-negative, indicating that CD9 expression in CAFs-EVs is a favorable prognostic marker for malignant melanoma patients." (PMID 37575250, 2023). "Similarly, CD9 was lost in melanomas with II and III Clark level and re-expressed in 20 of the 64 melanomas with IV level (31%) and in 24 of the 32 with V Clark level (75%)." (PMID 35563166, 2022). "The most interesting finding was that all 44 CD9 stained melanomas (100%) presented sentinel node positivity (CD9+N1) and, consequently, none of the CD9 negative melanomas (CD9-N0) had sentinel lymph node micrometastases." (PMID 35563166, 2022). "CD9 expression in cells forming the squamous epithelium from which the tumors arose was not always conserved in melanomas." (PMID 35563166, 2022). "Several other tetraspanins, mainly CD9, CD81, CD82 and CD151 have been described to regulate proMMP-2 and/or proMMP-9 expression in cancer cell lines from liver, kidney, breast and lung carcinomas, fibrosarcomas and melanomas." (PMID 32455575, 2020). "CD81 interacts with CD9 (another member of the tetraspanin family), which is also significantly upregulated in TCam-2 cells (supplementary ), and both play an important role in the TGF beta signaling pathway in melanoma cells." (PMID 31565104, 2019). "Interestingly, similar outcome were observed with two other melanoma cell lines, A375 and C8161, exposed to FEMX‐I cell‐derived CD9‐GFP+ EVs, indicating that CD9 Fab inhibits the uptake of EVs." (PMID 30982221, 2019). "Elevated luminescence signals of MT-CO2/CD9 were detected in both melanoma tissue-derived EVs and non-melanoma cell-derived EVs." (PMID 31497264, 2019). "Among the proteins that were found in MVs as well as both exosome subpopulations isolated from melanoma cells, we found suggested EV and exosome marker proteins ALIX, TSG101, CD9, CD81 and CD63, however their relative abundance was higher in LD-Exo and HD-Exo as compared to MVs." (PMID 26931825, 2016).
melanoma (continued). "It is supposed that CD9, expressed by ECs rather than melanoma cells, is localized at sites of contact between melanoma and ECs." (PMID 24520284, 2014). "Our results showed that CD9 expression exhibited a significant predictive effect on SNB status, suggesting that it could serve as a useful addition to a marker panel for selecting melanoma patients, in particular with intermediate thickness melanoma for SNB." (PMID 35563166, 2022). "However, in later stage melanoma cells when TGFβ signaling is high, EWI-2 is downregulated, which allows its two tetraspanin partners CD9 and CD81 to engage with TGFβ receptors and stabilize a signaling active TGFβ receptor complex resulting in increased Smad signaling." (PMID 32274581, 2020). "These EVs were enriched with vesicular marker proteins (CD9, CD81 and Tsg101), tyrosinase, F4/80, alpha-smooth muscle actin and E-selectin, suggesting that melanoma cell-, macrophage-, fibroblast- and endothelial cell-derived EVs are present in the melanoma microenvironment." (PMID 26082317, 2013). "Notably, CD81 and CD9-positive vesicles derived from melanoma Mel501 cells, although not very abundant, exhibited a high level of protein expression (MFI) on single Bodipy-exo, indicating that the vesicles, although not very represented, are enriched in these tetraspanins." (PMID 40643510, 2025). "In this study, using a transwell migration assay, we found that both dextran-coated iron oxide nanoparticles (dex-IO NPs) and ionomycin stimulated exosomal CD9 expression in human MSCs (hMSCs); however, hMSCs could not deliver them to melanoma cells to affect cell migration." (PMID 33572290, 2021).